KIF11 (kinesin family member 11)
Diseases named in the same sentence as KIF11 in open-access papers (continued):
Sharing a sentence is not in itself a finding about the gene and the disease.
ovarian carcinoma (19 papers, 2012 to 2026). A malignant neoplasm originating from the surface ovarian epithelium. "Overall, wheldone was found to be a fungal metabolite that inhibits KIF11 in chemoresistant ovarian cancer, with future studies needed to improve its pharmacokinetics and delivery." (PMID 41881190, 2026). "Ovarian cancer patients with higher KIF11 expression were resistant to chemotherapy and targeted therapy." (PMID 36742345, 2022). "In one previous study, 4 of 16 identified hub genes in the studied sample (CCNB1, CENPF, KIF11, and ZWINT) were associated with decreased OS of patients with ovarian cancer." (PMID 34785763, 2022). "We also found that TRAF4 and KIF11 were upregulated in ovarian carcinomas and that their level of expression was positively correlated with that of DR6." (PMID 30186750, 2018). "KIF11 inhibition has also been reported to kill human ovarian carcinoma and leukemia cells via the intrinsic apoptotic pathway in a Bcl-2-sensitive manner." (PMID 23071517, 2012). "Furthermore, confirmed by a rescue experiment conducted on ovarian cancer cells, the proteins associated with the migration of these two pathways are activated by a complex combining death receptor 6 (DR6), TRAF4, and KIF11." (PMID 38672404, 2024). "In addition, KIF11 has been found to be the target of miR-424 and miR-381, playing roles in ovarian cancer." (PMID 38672404, 2024). "Meanwhile, KIF11 could reduce the inhibitory effects of DR6 knockdown on ovarian carcinoma cell migration, implying KIF11, to some extent, contributed to the cell mobility." (PMID 33968780, 2021). "For example, Bianhua Shi reported that KIF11 can promote the migration of ovarian cancer cells." (PMID 35140744, 2021). "KIF11 abnormalities in prostate cancer, ovarian cancer were found." (PMID 31888692, 2019). "The gene encoding this protein, ZWINT, was discovered to be overexpressed in ovarian cancer, among other genes (such as CCNB1, CENPF, KIF11) related with cell cycle, nuclear division and oocyte meiosis." (PMID 33445445, 2021). "The protein expression levels of CCNA2, CCNB1, CDC20, CDCA8, CDK1, KIF11 and TOP2A were high in ovarian cancer tissues, which was further confirmed via the HPA database." (PMID 34253236, 2021). "The bioinformatic obtained results have been validated by an in vitro ovarian cancer model, represented by SKOV3 cell line: silencing of KIF11 results in a significant reduction of cell proliferation probably due to induction of apoptosis, as demonstrated by the increased activation of Caspase 3/7." (PMID 38939361, 2024). "Notably, in separate but parallel investigations conducted by our team, we observed significant vulnerability of the spindle assembly motor proteins KIF11 and KIF15 and their binding partner TPX2 in epithelial ovarian cancer (unpublished data)." (PMID 37894278, 2023). "The findings above suggest that DR6 may play a notable oncogenic role in ovarian malignancy by interacting with TRAF4 and KIF11, and that DR6 may be an effective therapeutic target in ovarian cancer." (PMID 30186750, 2018). "have found that KIF11 was co-purified with death receptor 6 (DR6), which could promote cellular migration capacity mediated by MAPK/ERK and PI3K/AKT signaling pathways for ovarian carcinoma." (PMID 33968780, 2021).
pancreatic cancer (18 papers, 2015 to 2025). "Research indicates that higher levels of KIF11 are associated with increased tumor aggressiveness and reduced overall survival in pancreatic cancer patients." (PMID 40075652, 2025). "It has been previously established that KIF11 is associated with adverse outcomes in various diseases, such as gallbladder and pancreatic cancer, primarily due to its ability to modulate cell proliferation and vitality." (PMID 39166113, 2024). "In pancreatic cancer, kinesin family member 11 (KIF11) interacts with SREBP2, increasing its protein levels by attenuating ubiquitination-mediated degradation." (PMID 40308757, 2025). "Overexpression of KIF11 and RCC1 and underexpression of ADCY1 and SDK1 were detected in ~ 60% of grade 2 pancreatic cancer patients and associated with ~ 60% mortality in stages I and II." (PMID 38741142, 2024). "Intriguingly, we observed that KIF11 expressions and the mevalonate metabolic pathway were highly interrelated in pancreatic cancer from TCGA." (PMID 35619540, 2022). "In agreement with this, our cohort and TCGA studies demonstrated that KIF11 expression in pancreatic tumor tissues was indeed positively correlated with GIN markers, including MSH6, aneuploidy score, and fraction of genome altered." (PMID 34208606, 2021). "KIF11 was found overexpressed in human pancreatic cancer samples and promoted cell proliferation in an ATPase activity‐dependent manner, leading to the accumulation of polyploid cells." (PMID 32346924, 2020). "Over-expressed in PDAC cell lines and in pancreatic tumours (unpublished data), KIF11 is a mitotic kinesin that has been shown to promote cancer cell proliferation and tumour formation." (PMID 25886367, 2015). "Indeed, our recent pancreatic cancer data on KIF11 has revealed that the IRS scoring system was more informative for prognosis than PS itself." (PMID 34575892, 2021). "KIF11 is overexpressed in human cancers, including breast, lung, ovarian, and pancreatic cancer." (PMID 31991631, 2020). "KIF11 is highly expressed in blast crisis chronic myelogenous leukemia and pancreatic cancer." (PMID 33102593, 2020). "In particular, the overexpression of KIF11 and RCC1 and the underexpression of ADCY1 and SDK1 were detected in ~ 60% of tumor grade 2 pancreatic cancer patients and associated with around 60% mortality in stages I and II, which shows they can be early-diagnosis markers for pancreatic cancer." (PMID 38741142, 2024). "Furthermore, other studies of this group have revealed that a specific KIF11 inhibitor effectively suppressed cell proliferation and induced apoptosis in pancreatic cancer cell lines and tumor xenografts, as well as pancreatic cancer cell migration and invasion in vitro." (PMID 34208606, 2021). "The overexpression of KIF11 and RCC1 and the underexpression of ADCY1 and SDK1 were detected in ~ 60% of tumor grade 2 pancreatic cancer patients." (PMID 38741142, 2024). "Previous studies have reported the overexpression of KIF11, KIF15, and KIF18B in various malignancies, including gallbladder cancer, oral cancer, meningioma, pancreatic cancer, and osteosarcoma, supporting our findings." (PMID 37711200, 2023). "KIF11 was found overexpressed not only in MPM human tumor samples and MPM human cell lines, but also in blast crisis chronic myelogenous leukemia and pancreatic cancer." (PMID 32849853, 2020). "Taken together, our results showed that IMP3 expression promotes matrix adhesion, motility and invasion of pancreatic cancer cells by enhancing CD44 and KIF11 expression." (PMID 25886367, 2015). "In the present study, we aimed to determine the utility of KIF11 and KIF14 as markers of pancreatic cancer prognosis by analyzing the in-house IHC data and RNA-seq-based publicly available datasets in relation to clinicopathological traits and overall survival." (PMID 34208606, 2021).
pancreatic cancer (continued). "Furthermore, KIF11 and KIF14 mRNA levels were strongly correlated with one another in pancreatic tumor samples from the TCGA cohort, which could be also observed in our functional enrichment." (PMID 34208606, 2021). "A previous study reported that dimethylenastron, as a specific inhibitor of KIF11, significantly suppressed the migratory and invasive ability in PANC1 pancreatic cancer cells, but not their proliferative potential." (PMID 33968780, 2021).
prostate carcinoma (17 papers, 2012 to 2025). A carcinoma that arises from epithelial cells of the prostate gland. "KIF11 mediates mitosis and is involved in cell proliferation, and is also associated with bone metastasis in prostate cancer patients." (PMID 38331723, 2024). "The positive control siRNAs targeting known key regulators of the mitotic progression as well as prostate cancer cell proliferation, KIF11 and PLK1, were able to significantly decrease cell viability confirming thus transfection efficiency." (PMID 22761906, 2012). "The regulatory pathways SOX5-NEDD4L/PBX3, miR429-GNAQ/ANLN—RHOA, and miR429-ANLN—KIF11 may participate in the progression of the androgen-independent phenotype in prostate cancer." (PMID 29324665, 2018). "We also included as biological controls several genes known to be important for prostate cancer cell viability: AR, MYC, and KIF11." (PMID 29340039, 2017).
colorectal cancer (15 papers, 2018 to 2025). A primary or metastatic malignant neoplasm that affects the colon or rectum. "In colorectal cancer, elevated KIF11 expression correlates with well-differentiated histology and improved patient prognosis." (PMID 41614789, 2025). "KIF11 plays an important role in the cancer stem cells of esophageal squamous cell carcinoma and colorectal cancer." (PMID 35515103, 2022). "KIF11 was also identified as chromosome instability (CIN) gene in HCT116 colorectal cancer cell line." (PMID 34575892, 2021). "KIF11 promotes the formation of esophageal squamous cell carcinoma and colorectal cancer cell spheroids; spheroid formation is used to characterize CSCs." (PMID 31334127, 2019). "Additionally, in colorectal cancer (CRC), studies have demonstrated that altered expression levels of KIF11 and KIF14 are associated with patient outcomes." (PMID 40075652, 2025). "In the light of this and our protein data, it seems that KIF11 may produce a novel molecular target for colorectal cancer therapy." (PMID 34575892, 2021). "Genes, such as BOP1, KIF11, and MMS22L, are associated with the progression of various cancers, such as colorectal cancer, gastric cancer, lung, and esophageal cancer, but these genes may be linked with the development of BRCA." (PMID 31311202, 2019). "Furthermore, the prognostic value of KIF11 has been reported in oral cancer and colorectal cancer." (PMID 35186743, 2022).
Familial exudative vitreoretinopathy (15 papers, 2015 to 2026). Familial exudative vitreoretinopathy (FEVR) is a rare hereditary vitreoretinal disorder characterized by abnormal or incomplete vascularization of the peripheral retina leading to variable clinical manifestations ranging from no effects to minor anomalies, or even retinal detachment with blindness. "Pathogenic variants in KIF11 were subsequently detected in patients with familial exudative vitreoretinopathy (FEVR, OMIM 133780)." (PMID 36672954, 2023). "Mutations in KIF11 have been shown to cause familial exudative vitreoretinopathy associated with retinal detachment." (PMID 32290826, 2020). "Phenotypes from isolated Familial Exudative Vitreoretinopathy (FEVR) to systemic, syndromic presentations are attributable to KIF11 mutations." (PMID 40426739, 2025). "The associated diseases are known as microcephaly with or without chorioretinopathy, mental retardation, and lymphedema (MCLMR) and familial exudative vitreoretinopathy (FEVR), with the latter having reported KIF11 mutations in only a subset of the patients." (PMID 32811879, 2020). "KIF11 mutations were also discovered in 5 families with familial exudative vitreoretinopathy syndrome (FEVR), which thus belongs to the phenotypic spectrum caused by KIF11 mutations." (PMID 25934493, 2015). "Overall, we elucidate a β-catenin/KIF11/PRDX1 axis-dependent ferroptosis mechanism in familial exudative vitreoretinopathy, highlighting ferroptosis-targeting and antioxidant strategies as potential therapies." (PMID 41872221, 2026).
glioma (13 papers, 2010 to 2025). A benign or malignant brain and spinal cord tumor that arises from glial cells (astrocytes, oligodendrocytes, ependymal cells). "Upregulated KIF11 is negatively associated with overall survival (OS) and increased the chemotherapy resistance to 5-FU in glioma cells." (PMID 38672404, 2024). "In glioma, using KIF11 inhibitors significantly inhibits the expression of four types of matrix metalloproteinases (MMPs), including MMP-1/2/3/9, causing extracellular matrix turnover and cancer cell migration." (PMID 38672404, 2024). "Glioma data obtained with the TCGA database revealed 14–18 hub genes correlated with the worse survival prognosis and among them KIF11 is included." (PMID 38939361, 2024). "The identified DryNB included seven genes (KIF2C, CCNA2, NDC80, KIF11, KIF23, ANLN and CENPM) that were significantly associated with drug sensitivity or resistance of glioma patients to the targeted therapies." (PMID 31682596, 2019). "Human Protein Atlas data, shows that 83% of glioma patients express moderate to high levels of KIF11 and 90% of patients express at least some level of UBE2C." (PMID 31475119, 2019). "Among them, monastrol, a kinesin Eg5 (KIF11) inhibitor, has already demonstrated its efficiency in glioma in vitro and is currently under clinical development." (PMID 20885975, 2010). "KIF11 is a driver of glioma invasion, proliferation and self-renewal." (PMID 35774141, 2022). "In our previous study, we showed that CCNB1 and KIF11 are upregulated in human and canine glioma." (PMID 31475119, 2019). "In addition, KIF11 was identified as target-controlled cell growth and proliferation of glioma, and administration of a highly specific KIF11 inhibitor resulted in markedly reduced glioma tumor-initiating cells." (PMID 36837615, 2023). "Nonetheless, KIF11 knockdown led to the impairment of LUAD migration and invasiveness, while KIF11 knockdown in glioma cells reduced the PAK1-mediated cell migration." (PMID 41009541, 2025). "The clinical data verified the association of the identified genes (i.e., KIF2C, CCNA2, NDC80, KIF11, KIF23, ANLN, and CENPM) with the targeted therapy response and prognosis of glioma patients." (PMID 31682596, 2019). "Targeting KIF11 and UBE2C using small molecule inhibitors Ispinesib and Monastrol (KIF11 inhibitors) and NSC697923 (UBE2C inhibitor) in the canine model of glioma can potentially be a promising therapeutic strategy for future evaluation in human GBM." (PMID 31475119, 2019). "Several cell cycle regulatory genes are significantly upregulated in canine OG, however, we selected KIF11 and UBE2C, which are commonly upregulated in canine and human glioma, for further evaluation at the protein level." (PMID 31475119, 2019). "We then tested whether the temporal patterns of the prioritized 5 genes (i.e., KIF2C, CCNA2, NDC80, KIF11 and KIF23) could be used to predict drug sensitivities of different glioma cell lines." (PMID 31682596, 2019).
multiple myeloma (11 papers, 2012 to 2025). "Although most of the KIF11 inhibitors tested in clinical trials had only limited efficacy, Arry-520 (also known as filanesib) has shown clinical efficacy in patients with multiple myeloma and has entered phase 3 clinical trials." (PMID 39000337, 2024). "Filanesib is a kinesin spindle protein (KIF11) inhibitor which has recently been proposed for cancer treatment, specifically for multiple myeloma." (PMID 36104333, 2022). "Moreover, several KIF11 inhibitors entered clinical trials targeting multiple myeloma, acute myeloid leukemia, NSCLC, breast cancer, ovarian cancer, etc.." (PMID 39000337, 2024). "KIF11 inhibition may trigger the lysosomal cell death pathway also in other cell types since lysosome-stabilizing Hsp70 protects myeloma cells against cytotoxicity induced by dimethylenastron, a pharmacological inhibitor of KIF11." (PMID 23071517, 2012). "For instance, Filanesib, an inhibitor of KIF11, recently completed Phase 2 clinical trial for multiple myeloma treatment, with a response rate of 16% and progression free survival value of 1.6 months, now Filanesib has been scheduled to enter Phase 3 clinical trials for multiple myeloma." (PMID 37957153, 2023).
gastric cancer (10 papers, 2018 to 2024). A primary or metastatic malignant neoplasm involving the stomach. "KIF11 is overexpressed in GC 33; its knockdown via RNAi inhibits the number and size of spheres formed in gastric cancer stem cells." (PMID 34093807, 2021). "A high expression level of KIF11 has been reported in many types of human cancers, such as oral and gastric cancers." (PMID 29324665, 2018). "The new prognostic model, based on a gene signature developed by Chu and co-workers, shows a 9-gene signature to predict the overall survival of patients with gastric cancer in Asian population: among 9 identified genes, KIF11 emerged and these data could be extended to other populations." (PMID 38939361, 2024).